NANOG (Nanog homeobox)
Diseases named in the same sentence as NANOG in open-access papers (continued):
Sharing a sentence is not in itself a finding about the gene and the disease.
pancreatic cancer (continued). "In this study, we find that LIN28A increases the expression of stem cell markers SOX2, OCT4, LIN28B, c-Myc and NANOG in pancreatic cancer cells, and promotes their malignant behaviors including growth and invasion in vitro, further supporting the oncogenic potential of LIN28A." (PMID 26910839, 2016). "For example, lncRNA HOTTIP mediates HOXA9 expression to enhance Wnt/β–catenin pathway activation by binding to WDR5 in pancreatic cancer stem cells (PCSCs), leading to upregulated expression of CSC markers (CD44, CD133, and ALDH1) as well as stem-associated factors (SOX2, OCT4, LIN28, and NANOG)." (PMID 39937018, 2025). "Hence, the authors believed that the stem cell-associated genes (NANOG, POU5F1, and SOX2) may serve as promising markers and that BBR can be considered a potent anticancer agent for the treatment of pancreatic cancers." (PMID 34885950, 2021). "In pancreatic cancer, hCAP-18/LL-37 was strongly expressed by macrophages in response to tumor-derived Activin A, and increased CSC self-renewal, invasion, tumorigenicity, the expression of CD133 and of pluripotency-associated genes: KLF4, SOX2, OCT3/4 and NANOG." (PMID 34583655, 2021). "Linc-DYNC2H1-4 acts as a ceRNA for miR-145 and facilitates the expression of its target genes, including ZEB1, a key regulator of EMT, as well as CSC markers SOX2, OCT4, NANOG, and Lin28, thereby promoting EMT and CSC activity in pancreatic cancer." (PMID 39937018, 2025). "The results showed that three genes—NANOG, CK19, and INS—were significantly elevated in patients with pancreatic cancer compared to healthy controls." (PMID 40699634, 2025). "The mRNA expression of selected stem and progenitor genes (NANOG, INS, CK19) in peripheral-blood mononuclear cells has potential as a valuable marker for pancreatic cancer, with a notable correlation with coexisting inflammation." (PMID 40699634, 2025). "Although SPOP has been considered as a tumor suppressor in pancreatic cancer by targeting NANOG, however, the potential immunological role of SPOP in pancreatic cancer have rarely been estimated holistically." (PMID 39074086, 2024). "Subsequently, we performed immunofluorescence analysis for the human pancreatic cancer tissues and found that the expression of IL20RB was positively correlated with the expression of NANOG and SOX2." (PMID 38098005, 2023). "For example, in a pancreatic cancer tissue microarray analysis of 43 cases, high expression of NANOG predicted worse prognosis, and knockdown of both NANOG and OCT4 inhibited stemness of pancreatic cancer cells." (PMID 37614497, 2023). "MiR-205 is downregulated in pancreatic cancer, and in an in vitro model, the overexpression of miR-205 decreased the expression of both general stemness markers such as OCT-3/4 and NANOG, and more specific pancreatic CSC markers such as CD44 and ALDH1." (PMID 33562727, 2021). "Published data indicate a possible correlation between the expression of NANOG and AB209630 in human pancreatic cancer cells." (PMID 33643897, 2020). "Mint3 depletion decreased tumor sphere formation ability and expression of the stemness-related genes SOX2, NANOG, and LGR5 in pancreatic cancer cells." (PMID 32826949, 2020). "We showed that, in one patient with pancreatic cancer, the expression of a truncated form of SPOP (p.Q360*) lacking the nuclear localization signal led to nuclear accumulation of NANOG, which promoted growth and metastasis of pancreatic cancer cells." (PMID 31624231, 2019). "In studies with pancreatic cancer cells, hypoxia and HIF have been shown to be important in the expression of IL-6, miR-21, miR-210 and VEGF as well as the CSC-related factors: NANOG, OCT-4 and EZH2." (PMID 28611316, 2017). "In an orthotopic pancreatic tumor model, CDF also inhibited the expression of EZH2, NOTCH-1, CD44, EpCAM, and NANOG." (PMID 28611316, 2017).
pancreatic cancer (continued). "Notably, treating pancreatic cancer cells with Stattic, a STAT3 inhibitor, substantially reversed the upregulation of mRNA expression of tumor stemness markers (NANOG, SOX2 and POU5F1) induced by IL20RB overexpression." (PMID 38098005, 2023). "In the present paper, we found a positive correlation between the protein expression of stemness markers (NANOG and SOX2) and IL20RB in pancreatic cancer samples, suggesting that IL20RB may promote tumor stemness." (PMID 38098005, 2023). "Additionally, miR-205 is downregulated in pancreatic cancer and its overexpression decreases the expression of both general stemness markers such as OCT-3/4 and NANOG and more specifically pancreatic CSC markers, including CD44 and ALDH1." (PMID 38139352, 2023). "Bitter melon water extract could inhibit CD44+/CD24+/EpCAMhigh CSC populations, decrease CSC markers SOX2, OCT4, NANOG and CD44 and enhance gemcitabine sensitivity in pancreatic cancer models." (PMID 32726914, 2020). "Therefore, we used patient samples and cell lines of pancreatic cancer to examine whether SPOP activity may be associated with the onset or progression of this disease and, if so, whether SPOP exerts its effects through its role in promoting the ubiquitination-dependent degradation of NANOG." (PMID 31624231, 2019). "To confirm whether SPOP depends at least in part on NANOG to influence pancreatic cancer cell behavior, we constructed a SW1990-shSPOP#1/shNANOG cell line expressing shRNAs targeting SPOP and NANOG." (PMID 31624231, 2019). "Analyses of human tissue microarrays with pancreatic cancer and non-cancerous tissues could detect NANOG expression in metaplastic ducts, suggesting that NANOG is already involved in the early stages of carcinogenesis." (PMID 37461005, 2023). "Furthermore, CD44V3 knockdown significantly suppressed the expression of multiple stemness markers, including BMI1, KLF4, SOX2, and NANOG, indicating that, in accordance with CD44V, CD44V3 possesses stemness-maintaining ability and then promotes pancreatic cancer migration and invasion." (PMID 36292918, 2022). "In human pancreatic cancer cells, CD44+/CD133+/EpCAM+ CSC-like cells exhibited lower levels of let-7 expression, and this suppressed let-7 expression promoted the expression of pluripotency transcription factor, such as NANOG, SOX2, SOX9, OCT4, KLF4 and c-myc, to maintain CSCs." (PMID 34572067, 2021). "Forced expression of a 17 kDa MUC16-Cter fragment in pancreatic cancer cells mediated nuclear translocation of JAK2 which preferentially phosphorylated tyrosine 41 of histone H3 (H3Y41) in a STAT-independent manner and up regulated stemness specific genes LMO2 and NANOG." (PMID 29682172, 2018). "In conclusion, QYHJ exhibited a significant effect against the GEM resistance pancreatic cancer, which may be probably through the inhibition of cell migration, up-regulate the levels of lncRNA AB209630 and down-regulate the levels of miR-373, EphB2, and NANOG." (PMID 31147453, 2019).
glioblastoma (35 papers, 2012 to 2025). The most malignant astrocytic tumor (WHO grade IV). "As the roles of these genes are intimately involved with glioblastoma multiforme progression and exosomes are critical in intercellular communication, we conducted a detailed analysis of the association of the NANOG gene family with exosomes to identify diagnostic markers for cancer." (PMID 29787607, 2018). "Both NANOG and POU5F1 are well-known master regulators of pluripotency; specifically, NANOG is implicated in both normal neural stem cell self-renewal and tumorigenesis in glioblastoma multiforme (GBM), while OCT4 functions in the differentiation of neural stem cells into neurons." (PMID 26888867, 2016). "The stem cell niche of low oxygen upregulates the expression of NANOG and these conditions of hypoxia are also important for the maintenance of glioblastoma stem cells." (PMID 34638956, 2021). "To find out if h-NANOG can regulate CXCR4 expression in human cancer cells, we studied how changes in h-NANOG level affected the expression of CXCR4 in human glioblastoma and astrocytoma cell lines." (PMID 34638956, 2021). "Several studies have shown the presence of a core embryonic stem cell-like stemness signature in glioblastomas consisting of NANOG, OCT4, and SOX2." (PMID 30353164, 2019). "As expected, they were shown to inhibit the activation of luciferase from a NHD->Luc construct by co-expressed NANOG in U251 glioblastoma (GBM) cells." (PMID 30846719, 2019). "This zone containing NANOG+ HIF-1α+ RNApII-S2P-/low cells is considered a model corresponding to the “peri-necrotic niche” in glioblastoma tissues." (PMID 26799577, 2016). "In addition, NANOG expression was correlated with multipotency or proliferative invasion in a glioblastoma model, similarly supporting a role for NANOG in the stemness of normal and malignant neuronal cells." (PMID 36376495, 2022). "In addition, we found a correlation between NANOG and CXCR4 expression levels in tumor cell lines, further supporting a role for CXCR4 in NANOG-expressing glioblastomas." (PMID 34638956, 2021). "A recent study revealed that the induction of EGR1 could trigger glioblastoma cell dedifferentiation into a stem-like state, which involved the expression of pluripotent markers NANOG and OCT4." (PMID 34051854, 2021). "In addition, transfection studies in human glioblastoma cell lines revealed the requirement of NANOG to express CXCR4." (PMID 34638956, 2021). "Consequently, our results reveal that increased NANOG expression in glioblastoma with IDH1R132H is a potential molecular target for therapeutic strategies." (PMID 31151327, 2019). "Indeed, HDACi resistance was attenuated in IDH1R132H-expressing glioblastoma cells by the suppression of NANOG using small interfering RNAs." (PMID 31151327, 2019). "Overall, our finding suggested that HDACi resistance by IDH1R132H-induced NANOG, which attenuated by IDH1R132H inhibitor, AGI-5198, could be applied to improve therapeutic outcomes in glioblastoma patients with IDH1R132H mutation." (PMID 31151327, 2019). "Moreover, CXCR4 expression requires NANOG in human glioblastoma cells." (PMID 34638956, 2021). "In addition, CXCR4 expression is regulated by NANOG in glioblastoma cells." (PMID 34638956, 2021). "When CSCs derived from glioblastoma or CSC-depleted cultures of glioblastoma cells were exposed to low pH conditions, there was an upregulation of CSC markers such as OLIG2, OCT4, and NANOG." (PMID 39361163, 2024). "The aim of this study was to investigate the expression of four pluripotency-related genes (OCT4, NANOG, SOX2, and CARM1) in human glioblastoma (GBM)." (PMID 35274101, 2022). "The RR GBM cells were enriched with glioblastoma stem cells (GSCs) confirmed by specific marks of CD133, OCT4, SOX2, NANOG, and HER2 by Western blot with elevated CD133/HER2 population identified by flow cytometry analysis." (PMID 35314680, 2022).
glioblastoma (continued). "Moreover, HH is involved in regulating tumor spheroid formations, as observed in the case of glioblastoma (GBM) neurospheres, by controlling NANOG.; nestin, BMI1, and gene expression." (PMID 35205721, 2022). "Recently, we have shown that culture on certain synthetic hydrogels rapidly induces expression of CSC markers, such as OCT4 and NANOG, more strongly than the conventional sphere culture and confers CSC activity on glioblastoma cells." (PMID 36497371, 2022). "Cells expressing proteins including SOX2, OCT4, pSTAT3, KLF4, NANOG, and SALL4 were identified as CSCs in Glioblastoma multiforme (GBM)." (PMID 33799834, 2021). "Our research opens a new line of study that allows us to deepen the relationship between NANOG and CXCR4 in glioblastoma cells." (PMID 34638956, 2021). "We chose NANOG since previous work showed the essential requirement for NANOG activity for human glioblastoma (GBM) growth in orthotopic xenografts, and it is apparently absent from many adult human tissues thus likely minimizing unwanted effects on normal cells." (PMID 30846719, 2019). "Western blotting showed that CD133, ALDH1, NANOG, ID1 and ID3 were downregulated in U251 and T98G glioblastoma cells upon ONC201 treatment at 72 h." (PMID 28767654, 2017). "First, the expression of SOX2, NANOG, HIF-1α, and RNApII-S2P in glioblastoma tissue was investigated by single-color immunohistochemistry." (PMID 26799577, 2016). "Here, we demonstrate that U87 glioblastoma 3D neurospheres culture conditions can partially recapitulate the CSC chemoresistance and invasive molecular signature by increasing PROM1, SOX2, and NANOG expression." (PMID 36497426, 2022). "Moreover, the PTEN, an inhibitor for the PI3K signaling pathway, represses the expression of stemness and drug resistance markers OCT4, SOX2, NANOG and MDR1 in glioblastoma." (PMID 30944375, 2019). "The biological importance of SOX2+ (or NANOG+) HIF-1α+ RNApII-S2P-/low tumor cells was also confirmed by our finding that these cells were found exclusively in glioblastoma tissues but not in grade II–III astrocytoma tissues." (PMID 26799577, 2016). "The expression of four pluripotency-related genes was investigated (OCT4, NANOG, SOX2, and CARM1) in the most malignant primary human brain tumor, glioblastoma (GBM)." (PMID 35274101, 2022). "Furthermore, in glioblastoma the inhibition of CXCR4 and CXCL12 by a miRNA cluster blocked tumor development in mice with cancer cells implanted into the striatum and decreased the expression of OCT4 and NANOG in vitro." (PMID 36118530, 2022). "Similarly, Spy1 knockdown suppressed the expression of canonical stem cell transcription factors NANOG and OCT4 in both GBM cell lines and patient-derived GSC11 glioblastoma stem cells." (PMID 34488821, 2021). "Interestingly, all studied glioblastoma-derived spheres (WG14, L0125, L0627) did not express NANOG or OCT4A, essential transcription factors that regulate self-renewal and pluripotency of embryonic stem cells." (PMID 36900355, 2023). "Similarly, in patient-derived GSC11 glioblastoma stem cells, glimepiride significantly increased CLIP3 expression and reduced NANOG and OCT4 expression without IR exposure due to its high intrinsic radioresistance." (PMID 34488821, 2021).
hepatocellular carcinoma (35 papers, 2013 to 2025). A malignant tumor that arises from hepatocytes. "Down-regulation of NANOG in human hepatocellular carcinoma decreases the expression of SOX2, OCT4, and KLF4, giving rise to the reduced proliferation, invasion, and migration of cancer cells[34 ▶]." (PMID 32429647, 2020). "NANOG is often overexpressed in hepatocellular carcinoma, particularly in cancer stem cells." (PMID 38846985, 2024). "Likewise, through pharmacological activation with A769662 or through transfection, AMPK upregulation resulted in reduced expression of stem cell markers, including NANOG, in hepatocellular carcinoma cells." (PMID 36114703, 2022). "Furthermore, our findings support the theory of a consistent collapse in the Hippo axis, as well as an expression of the stemness factor NANOG in high alpha-fetoprotein-expressing hepatocellular carcinomas." (PMID 25502816, 2014). "In hepatocellular carcinoma (HCC) cell lines, NANOG overexpression is correlated with advanced disease stages (III and IV TNM stages)." (PMID 39547513, 2024). "Hepatitis B virus (HBV) encoded X antigen (HBVx) was reported to activate stemness associated factors OCT-4, NANOG, β-catenin, KLF 4, and EpCAM as well as induce cell migration and sphere formation in hepatocellular carcinomas (HCC)." (PMID 37954619, 2023). "Moreover, IL25 could promote proliferation and sustain self-renewal of NANOG positive hepatocellular carcinoma by activating NF-κB and JAK/Stat3 pathways." (PMID 35359953, 2022). "In hepatocellular carcinoma (HCC), NANOG, a well-known stem cell marker, suppresses OXPHOS and mitochondrial ROS production as well as activating FAO in order to support CSCs properties including self-renewal, tumorigenesis, and chemoresistance." (PMID 34348794, 2021). "NANOG promoter hypomethylation and gene upregulation were found in metastatic human liver cancer cells and human hepatocellular carcinoma (HCC) primary tumor tissues." (PMID 24023739, 2013). "A similar study showed that HOXB7 was highly expressed in hepatocellular carcinoma, where it promoted cell proliferation, upregulated cancer stem cell markers EPCAM and NANOG, enhanced c-Myc and Slug expression, and promoted tumor growth." (PMID 41040515, 2025). "Coexpression of OCT4 and NANOG stimulates CSC properties and invasiveness through Stat3/ Snail signaling in hepatocellular carcinoma, while the knockdown of OCT4 decreases invasiveness in pancreatic and gastric cancer cells." (PMID 37529165, 2023). "In hepatocellular carcinoma derived CSCs, LPS based inflammatory mediators were shown to enhance the expression of stemness genes OCT4 and NANOG via IGF-IR signalling pathway." (PMID 37954619, 2023). "Previous reports also showed NANOG-mediated ICAM1 expression regulation in hepatocellular carcinoma, however, ICAM1 was conversely upregulated by NANOG therein." (PMID 31619256, 2019). "For example, NANOG is induced by toll-like receptor 4 (TLR4) signaling via the phosphorylation of E2F1, and the downregulation of NANOG slows down hepatocellular carcinoma (HCC) progression induced by alcohol, a Western diet, and hepatitis C virus protein in mice." (PMID 36833320, 2023). "In concordance with a previous study in hepatocellular carcinoma, we found that KLF5 inhibition dramatically decreased the spheroid growth and downregulated the expression of stem cell markers such as CD44, CD133, NANOG and OCT4 in EOC cells." (PMID 33424607, 2020). "In addition, clone formation and sphere formation of hepatoma cells were accelerated and cancer stem markers including EPCAM and NANOG were up-regulated." (PMID 28646927, 2017).
hepatocellular carcinoma (continued). "Other stemness-related markers, such as CD133, NANOG, and SOX2, are upregulated in hepatocellular carcinoma cell lines HepG2 and HCC-LM3, overexpressing AP4." (PMID 33567514, 2021). "However, a previous report indicated that while NANOG bound to the ICAM1 promoter region in CIC-like hepatocellular carcinoma cells, OCT4 and SOX2 did not." (PMID 31619256, 2019).